INPP5D (inositol polyphosphate-5-phosphatase D)
Description:
Phosphatidylinositol (PtdIns) phosphatase that specifically hydrolyzes the 5-phosphate of phosphatidylinositol-3,4,5-trisphosphate (PtdIns(3,4,5)P3) to produce PtdIns(3,4)P2, thereby negatively regulating the PI3K (phosphoinositide 3-kinase) pathways. Also, is able to hydrolyze the 5-phosphate of phosphatidylinositol-4,5-bisphosphate (PtdIns(4,5)P3), 1D-myo-inositol 1,4,5-trisphosphate and inositol 1,3,4,5-tetrakisphosphate. Acts as a negative regulator of B-cell antigen receptor signaling. Mediates signaling from the FC-gamma-RIIB receptor (FCGR2B), playing a central role in terminating signal transduction from activating immune/hematopoietic cell receptor systems. Acts as a negative regulator of myeloid cell proliferation/survival and chemotaxis, mast cell degranulation, immune cells homeostasis, integrin alpha-IIb/beta-3 signaling in platelets and JNK signaling in B-cells. Regulates proliferation of osteoclast precursors, macrophage programming, phagocytosis and activation and is required for endotoxin tolerance. Involved in the control of cell-cell junctions, CD32a signaling in neutrophils and modulation of EGF-induced phospholipase C activity. Key regulator of neutrophil migration, by governing the formation of the leading edge and polarization required for chemotaxis. Modulates FCGR3/CD16-mediated cytotoxicity in NK cells. Mediates the activin/TGF-beta-induced apoptosis through its Smad-dependent expression.
Synonyms: SIP-145; SHIP-1; hp51CN; SHIP; SHIP1; p150Ship
Tractability: Small molecule: a drug acting on it is in phase 2 or 3 trials; a structure with a bound ligand is known. Antibody: UniProt places it where antibodies can reach, with high confidence; its Gene Ontology location is reachable by antibodies, with medium confidence. PROTAC: ubiquitination databases record sites on it; its protein half-life has been measured.
Target class: Enzyme; Phosphatase
Gene: Protein-coding gene on chromosome 2 (233,059,967 to 233,207,903, forward strand). Ensembl gene ENSG00000168918.
Subcellular location: Cytoplasm; Cell membrane; Membrane raft; Cytoplasm, cytoskeleton; Membrane
Subcellular location (Human Protein Atlas): Cytosol
Pathways (Reactome):
Immune System: Downstream TCR signaling; Interleukin receptor SHC signaling; Signaling by CSF1 (M-CSF) in myeloid cells
Metabolism: Synthesis of IP3 and IP4 in the cytosol; Synthesis of PIPs at the plasma membrane
Hemostasis: PECAM1 interactions
Gene Ontology:
Molecular function: inositol-1,3,4,5-tetrakisphosphate 5-phosphatase activity; inositol-polyphosphate 5-phosphatase activity; phosphatidylinositol-3,4,5-trisphosphate 5-phosphatase activity; phosphatidylinositol-4,5-bisphosphate 5-phosphatase activity; protein binding; phosphatidylinositol-3,4,5-trisphosphate 3-phosphatase activity; inositol-1,4,5-trisphosphate 5-phosphatase activity; phosphatase activity
Biological process: negative regulation of natural killer cell mediated cytotoxicity; negative regulation of bone resorption; negative regulation of neutrophil differentiation; negative regulation of signal transduction; phosphate-containing compound metabolic process; phosphatidylinositol biosynthetic process; positive regulation of B cell differentiation; regulation of immune response; signal transduction; T cell receptor signaling pathway; phosphatidylinositol dephosphorylation
Cellular component: cytoplasm; cytosol; membrane; membrane raft; plasma membrane; cytoskeleton
Genetic constraint (gnomAD): Loss-of-function variants: 30 observed, 107.29 expected, observed/expected ratio (o/e) 0.28, 90% interval 0.21 to 0.38. The upper end of that interval is the gene's LOEUF score, 0.38, which puts it in group 1 of 6, group 1 being the genes least tolerant of losing a copy. Missense variants: 934 observed, 1,279.3 expected, observed/expected ratio (o/e) 0.73, 90% interval 0.69 to 0.77. Synonymous variants: 520 observed, 530.73 expected, observed/expected ratio (o/e) 0.98, 90% interval 0.91 to 1.05.
Homologues: Orthologues: chimpanzee INPP5D (99% identical), macaque INPP5D (97% identical), dog INPP5D (90% identical), pig INPP5D (90% identical), rat Inpp5d (88% identical), mouse Inpp5d (88% identical), guinea pig INPP5D (85% identical), rabbit INPP5D (57% identical), tropical clawed frog inpp5d (56% identical), zebrafish inpp5d (53% identical), Drosophila melanogaster Synj (14% identical), Caenorhabditis elegans unc-26 (13% identical), and 4 more. Paralogues in human: INPPL1 (40% identical), SYNJ1 (18% identical), SYNJ2 (18% identical), OCRL (15% identical), INPP5B (14% identical), INPP5J (12% identical), INPP5F (12% identical), INPP5E (11% identical), FIG4 (11% identical), SACM1L (8% identical), INPP5K (7% identical), SH2D1A (3% identical), and 1 more.
Diseases named in the same sentence as INPP5D in open-access papers:
INPP5D is named in the same sentence as 163 diseases in open-access papers, as found by Europe PMC text mining. Sharing a sentence is not in itself a finding about the gene and the disease. The quoted sentences say what the papers report.
Alzheimer disease (27 papers, 2016 to 2025). A progressive, neurodegenerative disease characterized by loss of function and death of nerve cells in several areas of the brain leading to loss of cognitive function such as memory and language. "Genes that were both selective for and highly expressed in the microglial cluster were Tgfbr1, Cyth4, Ikzf1, Dock2, and Inpp5d, many of which are associated with Alzheimer’s Disease (AD)." (PMID 38263132, 2024). "Recently, our group and others have reported the impact of deficiency of Inpp5d in the mouse model of Alzheimer's disease that substantially exhibits amyloid pathology." (PMID 38923171, 2024). "SLC35A4 is related to epileptic encephalopathy, while H19, ADORA2A and INPP5D are linked to cognitive impairment and Alzheimer's disease." (PMID 39020437, 2024). "A noncoding variant (rs35349669) within INPP5D, a lipid and protein phosphatase restricted to microglia in the brain, is linked to increased susceptibility to Alzheimer's disease (AD)." (PMID 38923171, 2024). "INPP5D/SHIP1 is a microglial-expressed gene that has been associated with Alzheimer’s disease through genetic studies." (PMID 38016942, 2023). "Expression of INPP5D isoforms associated with transcription start sites in exon 1 and intron 14 was increased in individuals with high Alzheimer’s disease neuropathology." (PMID 36981033, 2023). "Recent genome-wide association studies have identified single-nucleotide polymorphisms within the INPP5D (SHIP-1) gene as a risk factor for the development of Alzheimer’s disease." (PMID 37830592, 2023). "Single nucleotide polymorphisms within the human SHIP-1 gene INPP5D are strongly correlated with the development of Alzheimer’s disease and associated pathology in the aging brain." (PMID 37901420, 2023). "The single nucleotide polymorphisms rs35349669 and rs10933431 within Inositol Polyphosphate-5-Phosphatase D (INPP5D) are strongly associated with Alzheimer’s Disease risk." (PMID 36981033, 2023). "A second INPP5 family member, INPP5D, has been associated with Alzheimer’s Disease and cognitive decline, further implicating this gene family in cognitive functions." (PMID 29311653, 2018). "Inositol polyphosphate-5-phosphatase (INPP5D) was reported to be associated with Alzheimer's disease (AD) through modulating the inflammatory process and immune response." (PMID 27750211, 2016). "A recent genome-wide association study discovered a new locus single nucleotide polymorphism (SNP, rs35349669) of INPP5D which was significantly associated with susceptibility to late-onset Alzheimer's disease (LOAD) in Caucasians." (PMID 27750211, 2016). "The inositol polyphosphate-5-phosphatase D gene (INPP5D) is a risk-conferring gene for Alzheimer’s disease (AD) specifically expressed in microglia in the brain, and negatively regulates the phosphoinositide 3-kinase pathway controlling cell migration, proliferation, and survival." (PMID 38379102, 2024). "While studies have reported that elevated expression of INPP5D within plaque‐associated microglia correlates positively with amyloid burden, the impact of Inpp5d deficiency in preclinical models of Alzheimer's disease varies depending on the mouse models and timing of the inhibition." (PMID 38923171, 2024). "Inpp5d is genetically associated with Alzheimer's disease risk." (PMID 38923164, 2024). "In addition, heightened expression of Inpp5d in plaque-associated microglia from preclinical Alzheimer’s Disease models implicate the SHIP-1 pathway in plaque clearance." (PMID 37901420, 2023). "Several genome-wide association studies have indicated that single nucleotide polymorphic (SNP) variants of the SHIP-1 encoding gene, INPP5D, are an Alzheimer’s disease risk factor and they are associated with Alzheimer’s disease-related neuropathology in humans." (PMID 34838047, 2021). "Moreover, a SNP in INPP5D, the gene coding for the CD22 downstream signaling partner SHIP-1, was associated with late-onset Alzheimer’s disease (LOAD)." (PMID 34140954, 2021).
Alzheimer disease (continued). "Although significant research has been directed toward understanding the role of INPP5D in Alzheimer's disease, numerous studies have primarily focused on its involvement in amyloid pathology." (PMID 38923171, 2024). "Specifically, it was found that Alzheimer’s disease (AD) is correlated with an increase in the expression of INPP5D, and the elevated SHIP1 levels are believed to be associated with microglial markers and amyloid plaque density." (PMID 38791291, 2024). "As NLRP3 inflammasome activity has been linked to many diseases and disorders, the identification of INPP5D as a member of this pathway would have therapeutic significance in other disease fields beyond Alzheimer’s disease." (PMID 38016942, 2023). "In this review, we summarize these discoveries and discuss the potential of leveraging INPP5D/SHIP1 as a therapeutic target for Alzheimer’s disease." (PMID 37895194, 2023). "To better understand INPP5D expression in the brain, we investigated INPP5D isoform expression as a function of rs35349669 and rs10933431, as well as Alzheimer’s disease neuropathology, by qPCR and isoform-specific primers." (PMID 36981033, 2023). "INPP5D (Inositol Polyphosphate-5-Phosphatase D) is selectively expressed in brain microglia and likely a crucial player in Alzheimer’s disease pathophysiology." (PMID 33941241, 2021). "Collectively, these findings indicate that dysregulation in AKT activity in microglia, brought about by defective negative regulation through changes in INPP5D, contributes to the development of Alzheimer’s disease." (PMID 34838047, 2021). "Additionally, recent findings suggested that conditional deletion of Inpp5d in microglia in Alzheimer’s disease models augmented phagocytosis, increasing plaque encapsulation and engulfment by microglia." (PMID 37830592, 2023). "The presence of the CACNA2D3 (0.938, 0.902 − 0.975, P = .001), INPP5D (0.844, 0.802 − 0.888, P < .001), RBM47 (0.937, 0.891 − 0.985, P = .011) and TBXAS1 (0.965, 0.934 − 0.998, P = .036) may be associated with a lower risk of Alzheimer’s disease." (PMID 39560568, 2024). "However, recent studies have started to elucidate the role of INPP5D in Alzheimer's disease." (PMID 38923171, 2024). "The list included several known disease genes, such as INPP5D (Alzheimer’s disease), RAB27B (major depressive disorder, MDD), SORL1 (Alzheimer’s disease) and ZNF184 (MDD and schizophrenia)." (PMID 34446921, 2021). "In this review, we aim to discuss the current knowledge of processes driving INPP5D transcription, the actions of its gene product SHIP1 in microglia and their relevance to AD, while examining its potential as a novel therapeutic target for Alzheimer’s disease." (PMID 37895194, 2023). "In addition, a novel variant with 47bp lacking from exon 12 increased expression in Alzheimer’s Disease brains, accounting for 13% of total INPP5D expression, and was found to undergo nonsense-mediated decay." (PMID 36981033, 2023).
leukemia (17 papers, 2010 to 2025). A malignant (clonal) hematologic disorder, involving hematopoietic stem cells and characterized by the presence of primitive or atypical myeloid or lymphoid cells in the bone marrow and the blood. "Reduced expression of the INPP5D gene encoding SHIP1 is seen in several human leukemias, like acute myeloid leukemia (AML), acute lymphoblastic leukemia (ALL), and chronic myeloid leukemia (CML)." (PMID 38791291, 2024). "It appears to be a more common event in leukemia than mutation of the INPP5D gene." (PMID 40725184, 2025). "Using IP–MS strategy in NB4 and U937 leukemia cell lines, we identified 49 potential NTAL protein interactors, including a few previously identified, such as Grb2, Lyn, and SHIP1/INPP5D, and new proteins not previously reported as NTAL interactors." (PMID 33971369, 2021).
acute myeloid leukemia (11 papers, 2012 to 2026). Acute myeloid leukemia (AML) is a group of neoplasms arising from precursor cells committed to the myeloid cell-line differentiation. "In patients with acute myeloid leukemia (AML), some mutations in the INPP5D gene encoding SHIP1 have been described, thereby implicating mutated SHIP1 in the pathogenesis of AML." (PMID 37443832, 2023). "Gene transfer of INPP5D has been shown to reduce proliferation in CD34+ cells from patients with acute myeloid leukemia (AML)." (PMID 23565812, 2013).
amyloid (11 papers, 2018 to 2025). "INPP5D is another gene also thought to mediate the microglial inflammatory response and is associated with both amyloid and tau pathology." (PMID 39807599, 2025). "Recent research has revealed that Inpp5d was upregulated in amyloid plaque–associated microglia in 5XFAD models of familial AD and that ablation of Inpp5d in these mice reduced amyloid pathology." (PMID 38923164, 2024). "Microglial Inpp5d deficiency increased the density of microglia near Aβ deposits, altered plaque-associated microglial gene expression signature, promoted amyloid encapsulation and engulfment by microglia, and protected against Aβ-induced neuronal dystrophy." (PMID 37986179, 2023). "Loss of Inpp5d alters amyloid pathology in models of amyloidosis." (PMID 38923164, 2024). "Previous studies have demonstrated elevated expression of INPP5D in both AD human brains and the amyloid pathology mouse model, 5XFAD, with a positive correlation between INPP5D expression and amyloid burden." (PMID 38923171, 2024). "In the 5xFAD amyloid mouse model, INPP5D expression increased with disease progression, particularly in plaque-associated microglia." (PMID 39596356, 2024). "Conversely, another study found that amyloid pathology was increased when Inpp5d was inducibly depleted in PSAPP mice." (PMID 38923164, 2024). "Together, these studies highlight the potential of INPP5D modulation in promoting microglia functions that can be protective in response to amyloid pathology." (PMID 38923171, 2024). "INPP5D (also known as SHIP-1) is an inositol polyphosphate-5-phosphatase whose expression in microglia increases with the progression of amyloid pathology in LOAD selectively in microglia near Aβ deposits." (PMID 37986179, 2023). "One study found elevated INPP5D mRNA expression in human AD brains that positively correlated with amyloid plaque density, and elevated Inpp5d mRNA and protein expression in 5xFAD mice throughout disease progression." (PMID 38017562, 2023). "Although previous work has focused on reducing the expression of Inpp5d in mouse models of amyloid, we aimed to determine the effects of both partial and total Inpp5d loss on the brain transcriptome at single‐cell resolution in both male and female wild‐type mice in the absence of amyloid." (PMID 38923164, 2024). "Interestingly, not only do we observe robust SYK upregulation around amyloid plaques (> 3-fold) but associated protein tyrosine phosphatases PTPN6 and INPP5D are also enriched (upregulated 6.0-fold and 2.7-fold respectively)." (PMID 30189875, 2018). "While Inpp5d is well‐studied in amyloid pathology, its role in tau pathology remains unclear." (PMID 38923171, 2024). "This study design with wild‐type mice is a critical step in understanding the function of Inpp5d without the confounding effect of amyloid pathology on cell transcriptomes, as is the case in humans before AD pathology starts." (PMID 38923164, 2024). "By not crossing Inpp5d−/− mice with any models of amyloidosis, we were able to investigate the effect of Inpp5d haploinsufficiency on the brain transcriptome in the absence of pathology—in other words, modeling the effects prior to disease onset." (PMID 38923164, 2024).
Crohn disease (11 papers, 2012 to 2023). A gastrointestinal disorder characterized by chronic inflammation involving all layers of the intestinal wall, noncaseating granulomas affecting the intestinal wall and regional lymph nodes, and transmural fibrosis. "INPP5D deficiency is associated with ileitis and it is both involved in maintaining ileal microbial homeostasis and reduced levels have been reported in individuals with Crohn's disease." (PMID 35410447, 2022).
lymphoma (9 papers, 2011 to 2024). A malignant (clonal) proliferation of B- lymphocytes or T- lymphocytes which involves the lymph nodes, bone marrow and/or extranodal sites. "Pulsatile INPP5D inhibition contributed to the enhancement of T and NK cell function and improved antitumor immunity and survival in mouse models of lymphoma and colon cancer." (PMID 39176091, 2024).
B cell lymphoma (7 papers, 2012 to 2025). "However, higher amounts of post-transcriptional regulation of the SHIP1-Gene INPP5D with the micro-RNA miR-155 have been shown to negatively affect the prognosis of B cell lymphoma in humans." (PMID 38791291, 2024). "INPP5D was reported to negatively regulate PI3K-generated signals, and deletion of INPP5D might lead to the disease progression of spontaneous B cell lymphomas." (PMID 35568951, 2022).
Obesity (6 papers, 2020 to 2025). Accumulation of substantial excess body fat. "Dock2 and Inpp5d, which exhibit an affected binding of miR-29b are involved in chemokine signaling and Fc gamma R-mediated phagocytose, thus, in pathways known to associate obesity with insulin resistance." (PMID 32350386, 2020). "Small molecule inhibitors of INPP5D are known to improve obesity and the metabolic syndrome related to aging and diet." (PMID 35145474, 2021).
pancreatic cancer (6 papers, 2011 to 2022). "It was also observed that apigenin can induce the level of inositol polyphosphate-5-phosphatase D (INPP5D), thus reducing the population of M2-like TAMs and eventually promoting anti-cancer immune responses in murine pancreatic cancer models." (PMID 34575983, 2021). "In 42 primary pancreatic tumors the RNA-expression of the FLI1 targets DKK1, INPP5D, IGFBP3 and additionally two members of the Wnt/β-catenin pathway, namely BCL9 and BCL9L, was investigated using quantitative real time PCR." (PMID 27539223, 2016).
viral infection (6 papers, 2011 to 2024). "Among the most mutated genes in the RSW breed are the genes related to immunity, T-cell receptor variable 20-like, mitochondrial antiviral signaling protein (MAVS), and INPP5D (SHIP1), which may be caused by selection for the resistance to viral diseases." (PMID 39456845, 2024). "For example, upregulated levels of APP, BIN1, and INPP5D are connected with increases AD risks but play inhibitory roles in some viral infections." (PMID 37962454, 2024).
lung carcinoma (5 papers, 2015 to 2025). "For lung cancer, we found 3 SNPs across three inositol phosphate metabolism genes with P < 0.001, including rs13021302 (INPP5D), rs11083841 (CALM3), and rs11668501 (ITPKC)." (PMID 25683757, 2015).